BRAF (B-Raf proto-oncogene, serine/threonine kinase)
Diseases named in the same sentence as BRAF in open-access papers (continued):
Sharing a sentence is not in itself a finding about the gene and the disease.
glioma (continued). "BRAFV600E mutation (Class I) and BRAF-fusions (Class II) have been detected in 90% of pediatric low-grade gliomas, whereas mutations in histone H3-encoding genes have been identified in 50% of pediatric high-grade gliomas." (PMID 41050069, 2025). "Trametinib has been evaluated in pediatric clinical trials for tumors with activation of the MAPK pathway and has been recently authorized, in combination with the BRAF inhibitor dabrafenib, for the management of childhood gliomas harboring BRAF V600E mutations." (PMID 40906910, 2025). "The ROAR trial also evaluated the dabrafenib–trametinib combination in BRAF V600E-mutated rare tumors, including high-grade and low-grade gliomas, showing a 54% ORR in low-grade glioma (LGG) and a 33% ORR in high-grade glioma (HGG), suggesting superior efficacy over vemurafenib alone." (PMID 40332392, 2025). "In contrast, the BRAF V600E mutation, common in pediatric gliomas, is associated with a pro-inflammatory and dysregulated TME, characterized by infiltration of immunosuppressive myeloid cells and exhausted cytotoxic T cells together with pro-inflammatory immune cells." (PMID 40527978, 2025). "We also observed a few BRAF mutations (1.43%) in the high SASP Score group of glioma." (PMID 40781221, 2025). "This included 67 patients with BRAF V600E-mutated gliomas, 56 pLGGs and 11 pHGGs." (PMID 40422539, 2025). "Class 1 BRAF mutations have been described in 3% of adult glioblastoma and up to 20% of pediatric glioblastoma and are considered a potentially valuable target in recurrent glioma." (PMID 40725122, 2025). "A 2015 population-based study found that while only 2.9% of pLGGs transformed to secondary high grade gliomas (sHGG), BRAF V600E mutations were present in 44% (8 of 18) of pLLGs that transformed to sHGG as compared to 6% (10 of 167) of pLGGs that did not transform." (PMID 39839763, 2024). "Our results showed that after the treatment of dabrafenib combined with trametinib, the PFS and OS of BRAF V600 mutation-positive glioma patients were 6.10 months and 22.73 months, respectively, which showed an anti-tumor activity and improvement of disease progression." (PMID 39172230, 2024). "For recurrent gliomas with BRAF V600E mutation, trametinib combined with dabraafenib can be used." (PMID 39118481, 2024). "BRAF V600 mutations – leading to mitogen-activated protein kinase (MAPK) pathway activation – can be found in 5–15% of low-grade gliomas, including PXA (60–80%), gangliogliomas (20–70%), pilocytic astrocytomas (10%), and less frequently in GBM (approximately 3%)." (PMID 39361075, 2024). "BRAF fusions and Class I mutations were most prevalent in children, while adult gliomas harbored a broad range of BRAF alterations, including oncogenic Class II/III alterations, copy number alterations, and otherwise unclassified alterations, all of which were rare in pediatric glioma." (PMID 36854806, 2023). "Specifically, in low-grade gliomas, marked PD-L1 expression has been observed in a subset of cases that occur independently of the mutation status of the “rapid accelerated fibrosarcoma B gene” (BRAF gene)." (PMID 38275375, 2023). "This suggests a biological overlap between histologically defined low- and high-grade gliomas, and may be associated with a better prognosis than expected when compared to BRAF wildtype and H3K27-mutant DMGs." (PMID 37629304, 2023). "Our study excluded H3K27M- and BRAF V600E-mutated IDH-wt gliomas." (PMID 37568598, 2023).
glioma (continued). "Recent efforts to elucidate the co-occurrence of BRAF alterations with other genomic mutations and patient outcomes in adult gliomas are limited by case numbers or a particular focus on specific alterations, such as canonical BRAFV600E mutations and BRAF amplifications." (PMID 36854806, 2023). "Moreover, we have recently isolated tumor cells from a patient with BRAFV600E-mutated high-grade glioma, pre-/post- BRAF+MEK inhibitor combination therapy." (PMID 37920169, 2023). "BRAF V600E oncogene mutations have been reported in multiple central nervous system (CNS) tumor types, and emerging evidence supports the use of targeted therapy in BRAF-mutated gliomas." (PMID 36619621, 2022). "The BRAF V600E mutation detected by immunostaining or molecular studies is expected in ganglioglioma but can be positive in many other tumors, including low-grade glioma, PXA, DNT, and other glioneuronal tumors." (PMID 36290809, 2022). "The optimal sequencing of BRAF-targeted therapy in BRAF-mutated gliomas/glioneuronal tumors remains unclear, and further prospective studies are required to guide the use of genome-matched therapy in this patient population." (PMID 36619621, 2022). "As building evidence suggests H3 K27M-mutant gliomas with concurrent BRAF mutations behave less aggressively than those with isolated H3 K27M mutations, this case may represent a unique subset of LGG with paired H3 K27M and MAPK alterations." (PMID 35484611, 2022). "We hypothesized that combinations of genes IDH1/2, 1p19q, TERTp, EGFR, BRAF, TERTp, 10q, and H3 status can stratify gliomas for risk and may even be superior to conventional histological grading for prognostication." (PMID 35558510, 2022). "An interim analysis from the phase II, open-label ROAR basket trial assessing the combination of BRAF/MEK inhibitor therapy with dabrafenib and trametinib in BRAF V600E-mutated gliomas reported objective response rates of 33% and 69% in the high-grade and low-grade cohorts, respectively." (PMID 36619621, 2022). "This seems to suggest the presence of a biological overlap between histologically defined low- and high-grade gliomas and may be associated with a better prognosis than expected, compared to BRAF wild-type and H3K27-mutant DMGs." (PMID 36727064, 2022). "In addition, a very recent study included binimetinib (a MEK inhibitor) with encorafenib (a BRAF inhibitor) in adults with recurrent BRAF V600-mutated high-grade glioma (NCT03973918)." (PMID 35628161, 2022). "Second, the rarity of BRAF-mutated glioma could be associated with long-term recruitment within clinical trials." (PMID 36686797, 2022). "The activating mutation in BRAF is a common change in pediatric low-grade gliomas." (PMID 35785151, 2022). "In phase II clinical trials of pediatric patients, MEK inhibitors have demonstrated efficacy in pretreated, non- neurofibromatosis type 1 (NF1), recurrent optic pathway and hypothalamic low-grade gliomas, as well as BRAF-mutated or NF1- associated low grade gliomas." (PMID 35480100, 2022). "The total frequency of BRAF mutations in gliomas remains below 6%." (PMID 35267432, 2022). "The BRAF V600E mutation inducing the constitutive activity of Raf is frequently detected in low-grade pleomorphic xanthoastrocytoma, ganglioglioma, extra-cerebellar pilocytic astrocytoma, and epithelioid GBMs instead of other types of high-grade glioma." (PMID 35785151, 2022). "Thus, it is a promising treatment strategy that is worth being further investigated in the treatment of BRAF V600E-mutated paediatric gliomas." (PMID 33557011, 2021). "The exact impact on the clinical prognosis and possible molecular mechanism of associated co-occurring genes with mutations or copy number alterations co-occurring with BRAF mutations remains unclear in adult glioma patients." (PMID 33980169, 2021). "So, the parallel occurrence of H3 and FGFR1/BRAF mutations within a single tumor may complicate the diagnostic decision towards a low grade or a high grade glioma." (PMID 33433639, 2021).
glioma (continued). "Finally, the MEK inhibitor, binimetinib, was investigated in a non-randomized open-label clinical study in 62 patients with encorafenib, a BRAF inhibitor, in patients with recurrent BRAF V600-mutated high-grade glioma (HGG)." (PMID 33919596, 2021). "Mutations in driver genes such as IDH and BRAF have been identified in gliomas." (PMID 34525976, 2021). "Successful treatment with BRAF inhibitors for BRAF-mutated gliomas has been recently reported." (PMID 33673070, 2021). "In the realm of primary CNS tumors, the BRAF V600E mutation has been implicated as a key driver for papillary craniopharyngiomas and certain gliomas, such as pilocytic astrocytomas, pleomorphic xanthoastrocytoma (PXA), ganglioma, and GBM, most commonly epithelioid GBM." (PMID 33799709, 2021). "Because genetic alterations are important in tumor development and progression and both BRAFV600E and BRAFAMP can activate the MAPK pathway, we investigated the different effects of these two BRAF alterations and the mutations associated on the survival of glioma patients." (PMID 33489866, 2020). "Although prognostic significance of BRAF alterations for these tumor entities is still inconclusive, a diagnostic utility for the differential diagnosis of pediatric gliomas, as well as a possible therapeutic utility, makes the assessment of their occurrence of growing clinical relevance." (PMID 32879641, 2020). "A mutation of BRAF, V600E, was associated with an improved overall survival among glioma patients." (PMID 31941467, 2020). "At MCC, 3% of patients with gliomas have BRAF mutations who could potentially benefit from this combination therapy." (PMID 31748891, 2020). "Importantly, the majority of low-grade gliomas is driven by alteration of the BRAF-pathway (BRAF-fusions, mutations) which are promising candidates for liquid biopsy tumor detection." (PMID 33260839, 2020). "Moreover, in a previous study investigating BRAF(V600E)-mutated high-grade glioma, we found a similar effect in comparing two models derived before and after treatment with a combination of dabrafenib and trametinib." (PMID 33353026, 2020). "Characteristics associated with BRAFAMP and BRAF mutation in gliomas." (PMID 33489866, 2020). "Precision medicine such as the combination of dabrafenib and trametinib in BRAF V600E mutated gliomas, or other tyrosine kinase inhibitors such as regorafenib or NTRK inhibitors, may be used in selected patients." (PMID 33375286, 2020). "Indeed, more and more case reports and ongoing clinical trials have been showing that CNS cancer patients harboring BRAF V600 mutations are responsive to BRAF (and MEK) inhibitors." (PMID 32879641, 2020). "Whether BRAF mutations are present in all cells in a glioma or only a subset of tumor cells remains controversial and certainly has the potential to affect tumor response to targeted therapy." (PMID 31466300, 2019). "BRAF V600E mutations have been described in a variety of adult and pediatric gliomas, including pleomorphic xanthoastrocytoma (PXA; 60–80%), ganglioglioma (20–70%), pilocytic astrocytoma (PA; 9–10%), low-grade glioma (LGG; 5–15%), pediatric glioblastoma (pGBM; 20%), and adult GBM (3%)." (PMID 31466300, 2019). "The mechanism of acquired resistance to dabrafenib in one pediatric glioma was identified as a novel in cis mutation in BRAF (BRAF V600E L514V), which, upon biochemical characterization, was found to enhance dimerization, thereby decreasing sensitivity to dabrafenib." (PMID 31466300, 2019). "Particularly in younger glioma patients as well as in patients with an epithelioid glioblastoma, screening for a V600E BRAF mutation is promising since, in these cases, targeted therapy with BRAF inhibitors seems to be a useful salvage treatment option." (PMID 29621181, 2018). "Activating mutation of BRAF is a common finding in pediatric gliomas." (PMID 27611946, 2017).
glioma (continued). "Interestingly, while loss of BRAF V600E at recurrence has been reported in adult gliomas, the two cases in our study (HGG12, HGG13) retained this mutation at recurrence." (PMID 29084603, 2017). "Among them is a report that pediatric glioma-associated KIAA1549:BRAF fusions may regulate neuroglial cell growth via the mTOR pathway, depending on cell-type." (PMID 26525348, 2015). "V600E mutations in full length BRAF are seen in a small percentage of PA (6%); however, they are much more common in grade II, and high grade malignant pediatric gliomas; accounting for 18% of grade II, 33% of grade III, and 18% of grade IV tumors (23% grades II-IV)." (PMID 25821557, 2015). "Furthermore, in an intracranial xenograft model of BRAF V600E-mutated glioma, mice were randomized to receive vector alone, BRAF inhibitor (PLX4720) alone, radiation alone, or a combination of both radiation and BRAF inhibitor." (PMID 23717811, 2013). "Recently published in vivo murine data suggest that BRAF inhibitors may be effective in high-grade gliomas expressing the BRAF V600E mutation." (PMID 23717811, 2013). "Additionally, we show that activating BRAF mutations play a central role in both low and high grade glial tumors." (PMID 23592488, 2013). "Additionally, 15–20% of high-grade pediatric gliomas express BRAF V600E, an activating mutation of the BRAF gene." (PMID 23717811, 2013). "OncoMap profiles also support a new molecular stratification of pediatric low-grade gliomas based on BRAF mutations that may have immediate clinical impact." (PMID 19924296, 2009). "However, the histopathological features, clinical presentation, presence of a BRAF mutation, and the sustained therapeutic response to targeted therapy collectively support the diagnosis of a low‐grade glioma, most consistent with pleomorphic xanthoastrocytoma." (PMID 40765221, 2025). "However, the prognostic impact of BRAF V600E mutations in gliomas remains uncertain." (PMID 40332392, 2025). "In addition, PCNSHS and glioma may also show overlapping molecular features, such as BRAF V600E mutation or BRAF gene fusion, CDKN2A/CDKN2B homozygous deletion, etc." (PMID 40231251, 2025). "In addition, targetable mutations as well as fusion genes need to be analyzed as they provide therapeutic options for pediatric cancer, such as BRAF fusions/mutation in low-grade gliomas and NTRK fusions in several tissue types showing promising results in pediatric clinical trials." (PMID 38357207, 2024). "Moreover, patients with IDH1 wild-type high-grade gliomas harboring BRAF or NF1 mutations and receiving trametinib monotherapy or in combination with dabrafenib had longer progression-free and overall survival than patients who did not receive genotype-matched targeted therapy." (PMID 38481999, 2024). "It has been shown that the BRAF V600E mutation was found in nearly 20% of low-grade glioma patients and this alteration may play an oncogenic role by constitutively activating the mitogen-activated protein kinase (MAPK) signaling pathway (also known as the RAS/RAF/MEK/ERK pathway)." (PMID 39172230, 2024). "Some gliomas, especially pediatric gliomas, may harbor proto-oncogene B-Raf (BRAF) mutations." (PMID 39597073, 2024). "Among the JH MTB cohort of patients with IDH1 wild-type high-grade gliomas who received targeted therapies, trametinib monotherapy or in combination with dabrafenib conferred radiographic partial response in 75% of patients harboring BRAF or NF1 actionable mutations." (PMID 38143440, 2023). "Thus, PXA-like tumors characterized by this BRAF mutation might be named as immune warm gliomas, which might partially explain their better response to therapies associating radiotherapy and temozolomide." (PMID 36831610, 2023). "BRAF mutations are a significant driver of disease in pediatric low-grade glioma, but the implications of BRAF alterations on the clinical course and treatment response in adult glioma remain unclear." (PMID 36854806, 2023).
glioma (continued). "Similarly, the use of v-Raf murine sarcoma viral oncogene homolog B (BRAF) inhibitors for tumors harboring BRAF V600E mutations, including pediatric low grade gliomas, gangliogliomas, pleiomorphic xanthoastrocytomas and Langerhans Cell Histiocytosis, has extended survival for many of these patients." (PMID 34041027, 2021). "This may be useful in up to 3% of glioma patients with BRAF mutations." (PMID 31748891, 2020). "However, in light of the barely improved overall survival of patients suffering from high grade gliomas besides maximal multimodal treatment, BRAF mutated subgroups remain interesting entities that need to be further assessed for their accessibility to specific treatment modalities." (PMID 31181803, 2019). "Additionally, we could detect an inhibitory effect on cyclin D1 expression, confirming previous data, suggesting it as a downstream target of oncogenic MAPK-signaling in BRAF-mutated glioma." (PMID 31391125, 2019). "Outwith the glioma biology field, it has been proposed that the BRAF V600E mutation may be responsible for the induction of growth arrest and senescence in melanocytic naevi, in a process termed “oncogene-induced senescence” whereby melanocytic naevi can remain in growth arrest for a lifetime." (PMID 25785246, 2015). "Studies about molecular alterations in gliomas revealed that approximately 60–70% of thalamic LGGs carry the KIAA1549-BRAF fusion, and approximately 15% carry the BRAF V600E mutation." (PMID 41596345, 2026). "For instance, the dabrafenib–trametinib combination has received FDA approval for BRAF V600E-mutant low-grade gliomas." (PMID 41514664, 2026). "Hyperactivating mutations such as BRAF V600E and BRAF–KIAA1549 fusions are frequently observed in pediatric and adult low-grade gliomas, such as PAs, gangliogliomas, and PXAs." (PMID 41514664, 2026). "Within the RAF family of serine/threonine kinases, BRAF is the predominant oncogenic driver in cancers, including gliomas, followed less frequently by CRAF and only rarely by ARAF." (PMID 41514664, 2026). "Other medications (Ulixertinib, Plixorafenib) related to BRAF mutant gliomas were under investigation among pediatric populations." (PMID 41596345, 2026). "As a result, due to its broad activity, resistance-evasion capacity, and brain penetration, NST-628 shows promise for treating a wide range of RAS- and RAF-driven CNS cancers, including those with KRAS, NRAS, or BRAF mutations." (PMID 41514664, 2026). "In pediatric low-grade gliomas, including OPGs, aberrations such as BRAF–KIAA1549 fusion and BRAF V600E mutation constitutively activate the MAPK pathway, driving uncontrolled tumor cell proliferation and contributing to treatment resistance." (PMID 40867225, 2025). "Recientemente se ha demostrado que dabrafenib y su combinación con trametinib resultan eficaces en glioma pediátrico con mutaciones BRAF V600, lo que justifica evaluar esta combinación como terapia de primera línea." (PMID 40977817, 2025). "Dabrafenib Plus Trametinib: This combination is FDA-approved for BRAF V600E-mutant low-grade gliomas among children 1 year and older." (PMID 40867225, 2025). "We observed frequent ERK pathway reactivation in human glioma specimens following BRAF inhibitors, most commonly through EGFR and PDGFRβ activation." (PMID 40900823, 2025). "METHODS: Functional assays were performed to evaluate the impact of BRAF V600E on stemness phenotypes of glioma stem-like cells (GSCs) and invasive phenotypes of GBM cells in vitro and in vivo." (PMID 41469702, 2025). "Here, we evaluate adaptive resistance in BRAF-mutant glioma models and examine the potential efficacy of an SHP2 inhibitor-based vertical combination strategy." (PMID 40900823, 2025). "In the BRAF V600E sample collection, the optical pathways glioma (OPG) displayed the highest detection rate." (PMID 39751690, 2025).